SRPK3 (SRSF protein kinase 3)
Description:
Serine/arginine-rich protein-specific kinase which specifically phosphorylates its substrates at serine residues located in regions rich in arginine/serine dipeptides, known as RS domains. Phosphorylates the SR splicing factor SRSF1 and the lamin-B receptor (LBR) in vitro. Required for normal muscle development (By similarity).
Synonyms: MSSK-1; MSSK1; STK23; XLID114
Tractability: Small molecule: a high-quality ligand is known; it belongs to a druggable protein family. PROTAC: ubiquitination databases record sites on it; a small molecule that binds it is known.
Target class: CMGC protein kinase group; Enzyme; Kinase; Protein Kinase; CMGC protein kinase SRPK family
Chemical probes: MSC1186 (high quality)
Gene: Protein-coding gene on chromosome X (153,781,001 to 153,785,768, forward strand). Ensembl gene ENSG00000184343.
Subcellular location: Nucleus; Cytoplasm
Gene Ontology:
Molecular function: protein binding; protein serine/threonine kinase activity; ATP binding; protein kinase activity; protein serine kinase activity
Biological process: intracellular signal transduction; muscle tissue development; regulation of mRNA processing; spliceosomal complex assembly
Cellular component: cytoplasm; nucleus
Homologues: Orthologues: chimpanzee SRPK3 (97% identical), guinea pig SRPK3 (94% identical), pig SRPK3 (94% identical), rat Srpk3 (94% identical), mouse Srpk3 (94% identical), macaque SRPK3 (92% identical), dog SRPK3 (91% identical), zebrafish srpk3 (70% identical), tropical clawed frog srpk2 (69% identical), Drosophila melanogaster SRPK (50% identical), Caenorhabditis elegans spk-1 (49% identical), Drosophila melanogaster CG8565 (37% identical), and 8 more. Paralogues in human: SRPK2 (63% identical), SRPK1 (58% identical), NLK (19% identical), MAPK10 (17% identical), MAPK8 (17% identical), MAPK11 (16% identical), MAPK14 (16% identical), MAPK9 (16% identical), MAPK7 (16% identical), CILK1 (16% identical), MAPK12 (16% identical), MAK (16% identical), and 7 more.
Diseases named in the same sentence as SRPK3 in open-access papers:
SRPK3 is named in the same sentence as 16 diseases in open-access papers, as found by Europe PMC text mining. Sharing a sentence is not in itself a finding about the gene and the disease. The quoted sentences say what the papers report.
Intellectual disability (3 papers, 2020 to 2023). "SRPK2 deletions and SRPK3 point mutations have been identified in intellectual disability patients, which are predicted to disrupt SRPK kinase activity and downstream signalling." (PMID 37607329, 2023). "Interestingly, the discovery of SRPK2 heterozygous deletions and SRPK3 amplifications associated with intellectual disability suggests that gene dosage is critical for correct regulation of SRPK signalling." (PMID 37607329, 2023). "Therefore, we propose that SRPK2 deletion or SRPK3 mutation may disrupt RNF12 function during development or maintenance of specific neuronal populations, leading to intellectual disability." (PMID 33080171, 2020). "However, there is also evidence of SRPK3 and RNF12 gene amplifications in intellectual disability, suggesting that elevated SRPK signalling may also lead to neurodevelopmental phenotypes." (PMID 37607329, 2023).
centronuclear myopathy (2 papers, 2009). Centronuclear myopathy (CNM) is an inherited neuromuscular disorder characterized by clinical features of a congenital myopathy and centrally placed nuclei on muscle biopsy. "SRPK1 and SRPK2 are widely expressed in mouse embryonic tissues while SRPK3 (Stk23) is a muscle specific protein kinase whose elimination leads to centronuclear myopathy." (PMID 19851455, 2009). "It has been reported that MEF2C directly activates the expression of a muscle specific protein kinase Srpk3 and Srpk3-null mice exhibit widespread centronuclear myopathy via an unknown mechanism." (PMID 19400950, 2009).
Skeletal myopathy (2 papers, 2024). "A study showed that the association between variants on the TTN and RBM20 genes was responsible for a cardiomyopathy phenotype, and even more recently, the association of TTN and SRPK3 variants was associated with a skeletal myopathy phenotype." (PMID 39684706, 2024). "We propose that digenic inheritance of deleterious changes impacting both the protein kinase SRPK3 and the giant muscle protein titin causes a skeletal myopathy and might serve as a model for other genetic diseases." (PMID 38429495, 2024).
COVID-19 (1 paper, 2021). A disease caused by infection with severe acute respiratory syndrome coronavirus 2. "SRPK1 is highly expressed in most tissues and mostly associated with DNA and RNA processing, while SRPK3 is involved more specifically in muscle related functions and as such could be linked to cardiac complications observed in some COVID-19 patients." (PMID 34019655, 2021).
rhabdomyosarcoma (1 paper, 2022). A rare aggressive malignant mesenchymal neoplasm arising from skeletal muscle. "The documented role that SRPK3 plays in cancer is limited to a tumor suppressor in rhabdomyosarcoma." (PMID 35463320, 2022). "More specifically, SRPK3 was reported to be downregulated in rhabdomyosarcoma cells, and its expression promoted the splicing of MEF2Cα2 isoform and induced differentiation." (PMID 35463320, 2022). "Worth note is that this study also showed that restoration of SRPK3 expression or MEF2Cα2 inhibited proliferation and anchorage-independent growth of rhabdomyosarcoma cells." (PMID 35463320, 2022).
X-linked intellectual disability (1 paper, 2020). An X-linked intellectual deficiency in which not enough information is known, reported or published to indicate whether a gene causes non-syndromic or syndromic presentations. "Interestingly, several point mutations within the SRPK3 kinase domain (bottom) have been reported in X-linked intellectual disability." (PMID 33080171, 2020).
myopathy (1 paper, 2024). A disease of the muscle in which the muscle fibers do not function properly. "Noteworthy, the first example of digenism in myopathies was provided with the identification of the co-segregation of deleterious variants in SRPK3 and TTN in patients with progressive childhood-onset skeletal muscle myopathy with cores and centralized nuclei." (PMID 38982518, 2024). "Lastly, digenic inheritance with co-occurrence of heterozygous truncating variants in TTN and on the X-chromosomal SRPK3 gene, encoding a protein kinase, was found in three families with core myopathy." (PMID 38982518, 2024).
SRPK3 also shares sentences with these, for which no sentence is quoted: cardiac diseases (1 paper); cardiomyopathy (1); chronic kidney disease (1); genetic diseases (1); neuromuscular genetic disease (1); Parkinson disease (1); Parkinsonism (1); psychiatric disorder (1); tumor (1).